S100A4 (S100 calcium binding protein A4)
Diseases named in the same sentence as S100A4 in open-access papers (continued):
Sharing a sentence is not in itself a finding about the gene and the disease.
glioma (continued). "This could be due to S100A4, and upon depletion of S100A4, anti-VEGF therapy in mice bearing glioma was more efficacious." (PMID 37901250, 2023). "A further study indicated that low-grade glioma, which do not express S100A4, would be more incline to migrate along meninges and blood vessels, while S100A4 positive malignant glioma prefer to spread in areas of white matter." (PMID 36046652, 2022). "Finally, we isolated GFP+S100a4+ CD4+ T cells from S100a4+/- and S100a4−/− host gliomas and co-cultured them for 4 days with in vitro activated, fluorescently-labeled B6 CD3+ splenocytes." (PMID 35140215, 2022). "Another study reported that S100A4 played a crucial role in neutrophil-promoting tumor progression and S100A4 depletion could increase the effectiveness of anti-VEGF therapy in glioma." (PMID 31968004, 2020). "In addition, glioma-derived factors may affect the number of circulating and infiltrating neutrophils, whilst promoting GBM cell proliferation by upregulating S100A4 and thereby affecting their infiltration into tumours." (PMID 35625061, 2022). "In addition, immunofluorescence analysis showed the presence of Tregs (CD3+FOXP3+) and suppressive macrophages (GFP+CD206+) in S100a4−/− host gliomas, indicating that S100a4 is not required for lineage determination or cellular differentiation of these leukocytes." (PMID 35140215, 2022). "Double immunofluorescence analysis confirmed that CD45+ immune cells in S100a4−/− gliomas did not express S100A4, although S100A4 is expressed in a subset of glioma cells." (PMID 35140215, 2022).
pancreatic cancer (52 papers, 2005 to 2025). "A study found that S100A4 was associated with the low survival rate of pancreatic cancer, and TGFβ1 promoted EMT and increased invasiveness by up-regulating S100A4 expression level." (PMID 38431306, 2024). "As expected, many differential SE-associated genes in PSN1 were the key genes of pancreatic cancer, such as S100A4, S100A6, S100A2, NTSR1 and CDK5." (PMID 36318264, 2023). "Animals injected with S100A4-deficient tumor cells have significantly smaller pancreatic tumors relative to controls, strongly supporting a direct role of S100A4 in pancreatic cancer progression in vivo." (PMID 25677816, 2015). "P27Kip1 expression and cleaved caspase-3 are increased, while cyclin E expression is decreased, in S100A4-deficient pancreatic tumors in vivo." (PMID 25677816, 2015). "Tumor mass is remarkably decreased in animals injected with S100A4-deficient pancreatic tumor cells." (PMID 25677816, 2015). "By studying the underlying mechanisms of S100A4 in pancreatic cancer, it could be shown that S100A4 is upregulated by sonic hedgehog (Shh)-Gli-1 signalling as part of the hedgehog pathway, eventually resulting in EMT and further leading to metastasis." (PMID 32722137, 2020). "In this study, we examined the effects of S100A4 on the aggressive characteristics of pancreatic cancer cells in vitro by modulating S100A4 expression levels (loss and gain approaches), and pancreatic cancer growth in vivo by using an orthotopic human pancreatic cancer xenograft mouse model." (PMID 25677816, 2015). "S100A4 expression is associated with poor clinical outcomes of patients with pancreatic cancer." (PMID 25677816, 2015). "The effects of loss or gain of S100A4 were examined in pancreatic cancer cell lines." (PMID 25677816, 2015). "Although it remained unclear what causes S100A4 overexpression in thyroid carcinomas, it has been shown that hypomethylation of S100A4 gene correlates with gene activation and overexpression in human pancreatic carcinomas and colon adenocarcinoma cell lines." (PMID 16265347, 2005). "We investigated whether S100 proteins were associated with tumor grade, examined publicly available transcriptomic data from pancreatic cancer patients with high tumor purity, and confirmed the association of S100A4 with high-grade tumors and S100A14 expression with low-grade tumors." (PMID 36828915, 2023). "Thus, the increased Mmp-7 expression in our data might be associated with the rapid growth of pancreatic tumors in S100a4-Cre; Ext1f/f mice." (PMID 36809261, 2023). "The metastasis-associated gene S100A4 showed increased expression in invasive melanoma cell lines in this study, with S100A4 over-expression previously associated with a poor prognosis in a variety of human neoplasms such as stomach, colon, breast, melanoma, gallbladder, and pancreatic cancer." (PMID 20041153, 2009). "In line with the live cell imaging data, S100A4 mRNA expression was significantly increased by the exposure of contractile SMCs to pancreatic tumor organoid factors from cachectic patients (1.4-fold, p = 0.02)." (PMID 38339292, 2024). "Publicly available transcriptomic data from patients with pancreatic cancer and normal human pancreatic tissue also confirmed increased expression of both S100A4 and S100A14 in PDAC." (PMID 36828915, 2023). "Among these, S100A4 promoted pancreatic cancer progression and accelerated cell motility by activating the Src-FAK-mediated dual signaling pathway in pancreatic cancer cells." (PMID 36318264, 2023). "Next, we analyzed fibroblasts in the Pan02 S.C. pancreatic tumors of S100a4-Cre; Ext1f/f and control mice." (PMID 36809261, 2023). "Large variations in S100A4 levels in different pancreatic cancer cell lines have previously been reported." (PMID 37627239, 2023). "Among these S100 proteins, S100P and S100A4 have been most intensively investigated and both proteins have been shown to stimulate pancreatic cancer cell proliferation and tumor growth." (PMID 37627239, 2023).
pancreatic cancer (continued). "Subcutaneous transplantation experiments with murine MC38 colon cancer and Pan02 pancreatic cancer cells demonstrated substantially larger subcutaneous tumors in S100a4-Cre; Ext1f/f mice." (PMID 36809261, 2023). "Another study of pancreatic cancer liver metastasis also indicated that there were large amounts of secreted S100A4 proteins in macrophage culture supernatant in a secretome analysis." (PMID 35496059, 2022). "In conclusion, high S100A4 expression is not only a sign of pancreatic tumor malignancy but also a potential marker of PC metastasis and poor prognosis." (PMID 34527585, 2021). "Neutralizing monoclonal antibody 5C3 against S100A4 decreased endothelial cell migration, tumor growth and angiogenesis in immunodeficient mouse xenograft models of pancreatic cancer and melanoma." (PMID 34209679, 2021). "We also noticed that, S100A4 was up-regulated in all four pancreatic cancer cells relative to hTERT-HPNE cells." (PMID 34530774, 2021). "In breast/pancreatic tumors and normal breast/pancreatic tissues, Cd74high cells expressed fibroblast marker Fsp1/S100a4 whereas Pdgfra expression appeared to be restricted to tumor tissue only." (PMID 32455670, 2020). "Recent in vivo studies, including an orthotopic human pancreatic cancer xenograft mouse model, revealed that S100A4 activates focal adhesion kinase (FAK) and Src kinase, both involved in tumour progression and metastasis." (PMID 32722137, 2020). "Several studies also introduced S100A4 as a potential biomarker, as its expression correlates with malignancy, metastasis, invasion, and overall poor prognosis in pancreatic cancer." (PMID 32722137, 2020). "S100A4, another new bio-marker for activated PSCs, has been reported in murine pancreatic cancer-related fibroblasts." (PMID 29967585, 2018). "Gli1 expression in pancreatic cancer cells upregulates S100A4 and the Shh-Gli1 signaling pathway facilitates pancreatic cancer metastasis by the promotion of S100A4 gene transcription." (PMID 29069865, 2017). "Alteration of S100A4 and its downstream genes is crucial for pancreatic cancer development and the RNAi-mediated knockdown of S100A4 expression induces pancreatic cancer cell apoptosis and suppresses tumor cell growth, motility, and invasion." (PMID 29069865, 2017). "S100A4 was also shown to be a potential biomarker for other digestive system malignant tumors including pancreatic cancer and gallbladder cancer lymph node metastasis and prognosis." (PMID 29069865, 2017). "Only the studies reporting the correlation between S100A4 expression and clinicopathological characteristics or overall survival (OS) of patients with pancreatic cancer are enrolled." (PMID 26903691, 2016). "Together, these results indicate that S100A4 would be an attractive therapeutic target in pancreatic cancer." (PMID 25677816, 2015). "S100A4 downregulation remarkably reduces cell migration and invasion, inhibits proliferation, and induces apoptosis in pancreatic tumor cells." (PMID 25677816, 2015). "S100A4 downregulation increased the percentage of cells in G0/G1 phase, but decreases the percentage of cells in S phase, supporting that S100A4 plays a role in cell cycle progression in pancreatic tumor cells." (PMID 25677816, 2015). "The findings indicate that S100A4 is involved in mechanisms by which pancreatic cancer cells escape from TGFβ-induced effects (such as anti-proliferation)." (PMID 25677816, 2015). "In summary, the current work supports the role of S100A4 in pancreatic cancer progression in vivo, and provides novel insights into the signaling mechanisms by which S100A4 promotes tumorigenic capacity of pancreatic carcinoma cells." (PMID 25677816, 2015). "S100A4 expression is important for pancreatic tumor cells to avoid TGF-β1-induced growth inhibition and apoptosis." (PMID 25677816, 2015).
pancreatic cancer (continued). "In vitro S100A4 plays an important role in pancreatic cancer cell lines in cell migration and invasion, anchorage-independent growth, proliferation, and survival." (PMID 25677816, 2015). "S100A4 downregulation sensitized pancreatic cancer cells to TGF-β1-mediated growth inhibition and apoptosis." (PMID 25677816, 2015). "Our findings are consistent with their findings, that targeting S100A4 or its critical pathways is an attractive approach for the treatment of human pancreatic cancer." (PMID 25677816, 2015). "S100A4 also plays an important role in protecting pancreatic cancer cells against transforming growth factor beta (TGF-β)-induced growth inhibition and apoptosis." (PMID 25677816, 2015). "Although aberrant S100A4 expression is an independent biomarker of poor outcome, the molecular mechanisms by which S100A4 regulates pancreatic cancer progression in vivo are not completely understood." (PMID 25677816, 2015). "S100A4 expression is necessary to protect pancreatic cancer cells against TGFβ-induced growth inhibition and apoptosis." (PMID 25677816, 2015). "S100A4 has been reported to enhance pancreatic cancer cell invasion via the regulation of E-cadherin expression, and overexpression of S100A6 has been reported to result in the downregulation of E-cadherin." (PMID 25780452, 2015). "The silencing of S100A4 also resulted in decreased cell migration in Pan 2.03 and BxPC-3 pancreatic cancer cell lines (bars 2 & 3 versus bar 1, p < 0.01)." (PMID 25677816, 2015). "Nonetheless, this work also advances our knowledge by providing evidence demonstrating that S100A4 plays an important and direct role in pancreatic tumor growth in vivo." (PMID 25677816, 2015). "The role of S100A4 in tumor progression was studied by using an orthotopic human pancreatic cancer xenograft mouse model." (PMID 25677816, 2015). "A recent study further supports the role of S100A4 in pancreatic cancer progression by promoting angiogenesis." (PMID 25677816, 2015). "The findings provide evidence that S100A4 facilitates pancreatic cancer progression through promoting cell migration and invasion, anchorage-independent growth, angiogenesis, and tumor survival." (PMID 25677816, 2015). "This study demonstrates the critical role of S100A4 in tumorigenic potential of pancreatic cancer cells, such as migration, invasion, growth, and survival." (PMID 25677816, 2015). "This study provides evidence that S100A4 regulates cyclin E and p27Kip1 expression in vitro and in vivo in pancreatic tumor cells." (PMID 25677816, 2015). "S100A4 enables intracellular FAK and Src signaling events that operate as a dual signaling pathway and underlie the tumorigenic potential of pancreatic carcinoma cells." (PMID 25677816, 2015). "S100A4 enables FAK- and Src-mediated signaling that operate as a dual signaling pathway and underlie the tumorigenic potential of pancreatic carcinoma cells." (PMID 25677816, 2015). "As a matter of fact, numerous studies have indicated that the S100A4 protein levels in cancer tissue, pancreatic juice and serum of patients with pancreatic cancer were significantly increased." (PMID 25072505, 2014). "Especially, the S100A4 as a key moleculer marker promoting EMT process in pancreatic cancer was found to be upregulated more than 3 times in this study." (PMID 25072505, 2014). "Because S100A4 as a key EMT moleculer marker was found to be upregulated upon Gli1 in pancreatic cancer cells, we focused on the relationship between Shh-Gli1 signals and S100 genes family." (PMID 25072505, 2014). "Among these we found that up regulation of S100A4, NCAM1 and LIMK1 had already been associated with metastatic behavior in pancreatic cancer." (PMID 22078386, 2011). "Mahon and colleagues have demonstrated that S100A4 knockdown sensitizes pancreatic cancer cells to gemcitabine treatment, in addition to activating caspases and PARP, resulting in increased apoptosis and cell cycle arrest." (PMID 22028766, 2011).
pancreatic cancer (continued). "Therefore, this study involves the identification of various overexpressed protein members of the S100 protein family, including S100-A4, S100-A6, S100-A8, S100-A9, and S100-A11, to develop a successful multiepitope-based vaccine against pancreatic cancer." (PMID 38976715, 2024). "MMP-7 expression was significantly increased in the pancreatic tumors of S100a4-Cre; Ext1f/f mice." (PMID 36809261, 2023). "S100A4 was up-regulated in all four pancreatic cancer cells relative to hTERT-HPNE cells." (PMID 34530774, 2021). "The anti-S100A4 antibody 5C3 could show similar effects as it terminated endothelial tumour growth, cell migration and angiogenesis in vitro and in vivo for pancreatic cancer and melanoma models." (PMID 32722137, 2020). "Furthermore, knockdown of the transcription factor S100A4 enhances apoptosis of pancreatic cancer cells in response to gemcitabine via the induction of BNIP3 expression." (PMID 28968982, 2017). "Based on these findings, we speculate that S100A4 stimulates pancreatic cancer progression directly by promoting tumorigenic potential of cancer cells and indirectly by modulating tumor microenvironment including angiogenesis." (PMID 25677816, 2015). "In support of our assumption, RNAi-mediated knockdown of S100A4 has been reported to block cell growth and motility, and to induce apoptosis in the human pancreatic cancer cell lines BxPC-3, PANC-1 and MIA PaCa-2 via activation of pro-apoptotic signaling proteins including caspase-3, and caspase-9." (PMID 26138287, 2015). "Increased S100A4 expression is associated with increased Src and FAK activation in human pancreatic tumor tissues, and S100A4-deficient tumors show remarkably decreased FAK and Src activation in vivo in a pancreatic cancer mouse model." (PMID 25677816, 2015). "Whether S100A4 directly contributes to pancreatic cancer progression in vivo or is just a secondary effect of other changes during pancreatic cancer progression remains to be answered." (PMID 25677816, 2015). "As S100A4, FAK, and Src are all associated with poor prognosis in pancreatic cancer, it is important to understand whether they promote pancreatic cancer progression in a coordinated manner." (PMID 25677816, 2015). "S100A4 likely promotes pancreatic cancer progression in vivo through multiple mechanisms." (PMID 25677816, 2015). "Maybe S100A4 gene could be regulated by certain selectively activated signaling pathway at the same time in pancreatic cancer." (PMID 25072505, 2014). "Our data establish a novel connection between Shh-Gli1 signaling and S100A4 regulation, which imply that S100A4 might be one of the key factors in EMT mediated by Shh-Gli1 signaling in pancreatic cancer." (PMID 25072505, 2014). "Moreover, we attempted to identify new connections of Shh-Gli1 signaling pathway with S100 genes family and to demonstrate pro-metastatic function of S100A4 gene mediated by Shh-Gli1 signals in pancreatic cancer." (PMID 25072505, 2014). "Moreover, forced expression of S100A4 markedly accelerated the cell migration of pancreatic cancer cell lines with relatively low-level endogenous expression of S100A4, but did not affect their cell growth or invasion ability." (PMID 25310523, 2014). "Finally, the expressions of Shh, Gli1, S100A4 and E-cadherin in pancreatic cancer tissues were studied by using immunohistochemistry assays." (PMID 25072505, 2014). "Our findings provide a new connection establishing between Shh-Gli1 signals and S100A4 gene, which could be a therapy target for pancreatic cancer." (PMID 25072505, 2014). "An alternative could be other epigenetic modifications such as hypomethylation of the SOX4 gene, as exemplified by hypomethylated Claudin4, Lipocalin2, and S100A4, which accounts for their overexpression in pancreatic cancers." (PMID 23251334, 2012).